IL1B (interleukin 1 beta)
Diseases named in the same sentence as IL1B in open-access papers (continued):
Sharing a sentence is not in itself a finding about the gene and the disease.
Cognitive impairment (continued). "In prenatally LPS-treated offspring, we also demonstrated dysfunction of the CD200-CD200R interaction and IL-1β upregulation, which, in turn, both potentiate dopaminergic-induced neurodegeneration and contribute to cognitive impairment." (PMID 32829711, 2020). "ERK is known to mediate the expression of inflammatory mediators, including growth factors and pro-inflammatory cytokines (e.g., IL-1β) in an animal model of cognitive deficit." (PMID 33161894, 2020). "EAE mice, before demyelination, exhibit anxiety- and depression-like behaviors and cognitive impairment, which are dependent on the increased IL-1β and TNF-α levels in the hypothalamus." (PMID 32046097, 2020). "Accordingly, neflamapimod was evaluated in 20- to 24-month old Fischer rats with cognitive deficits, which previously have been described to be due to IL-1β-induced impairment of synaptic plasticity." (PMID 33275615, 2020). "In patients with early AD or mild cognitive impairment due to AD, levels of IL-1β and caspase-1 activity are significantly increased and ASC-bound Aβ is found in AD patients' brains." (PMID 32391019, 2020). "According to Qi and collaborators, the NKT treatment reduced the levels of TNF-α, IL-1β, and IL-6 in models of cognitive impairment and dementia in rats, corroborating the data from our pleurisy model." (PMID 32392744, 2020). "The low expression of TNF-α and IL-1β with the use of antibodies is thought to prevent neuronal damage and is expected to prevent the occurrence of Alzheimer’s disease or other cognitive disorders." (PMID 34367622, 2020). "Although IL-1β is critically involved in hippocampal plasticity and memory processes, high levels of this cytokine can lead to cognitive impairment." (PMID 33613281, 2020). "Previous experiments showed that the LPS-treatment cognitive impairment mice model enhanced the secretion of IL-1β, IL-6, and TNF-α and the expression of iNOS and COX-2 with increased NO production." (PMID 32796824, 2020). "Overexpression of IL-1β leads to MS-like pathologic phenotypes, including neurodegeneration, demyelination, and inflammation, together with cognitive impairments." (PMID 32046097, 2020). "The release of proinflammatory cytokines, such as TNF-α and IL-1β, has been reported as a critical factor in the development of cognitive deficits." (PMID 32655313, 2020). "Here, we showed that tibial fracture surgery induced cognitive deficit and production of proinflammatory cytokines interleukin-6 (IL-6) and IL-1β, along with microglia and astrocyte activation, neuronal damage, and blood-brain barrier (BBB) disruption." (PMID 31011286, 2019). "Hippocampal IL-1β-mediated neuroinflammation plays a pivotal role in surgery-induced cognitive impairment in aged rats." (PMID 30873011, 2019). "As a result, the N-methyl-D-aspartate signaling pathway was enhanced, whereas the IL-1β levels were reduced; both are responsible for ameliorating the cognitive defects that occur during the process of normal aging." (PMID 31803045, 2019). "Since blocking or neutralizing IL-1β in an AD mouse model largely protects from cognitive deficits, it led us to consider that the increased IL-1β level would drive potent neuroinflammatory changes contributing to neuronal death in the brain." (PMID 30402039, 2018). "Long-term rapamycin treatment in 18-months old C57BL6/129svJ mice was shown to reduce age-related cognitive deficits by reducing the pro-inflammatory cytokine IL-1β and enhancing N-methyl-D-aspartate (NMDA) signaling." (PMID 30237765, 2018). "In line with the induction of cognitive defects, excessive IL-1β affects long-term potentiation (LTP), the synaptic process which underlies learning and memory." (PMID 29674955, 2018). "In summary, our results propose that release of cytokines such as IL-1β, IL-6 and TNF-α and also MDA as lipid peroxidation index in brain tissue following TBI cause cognitive impairment and LTP insufficiencies." (PMID 30524680, 2018).
Cognitive impairment (continued). "PKR is increased in cerebrospinal fluid from patients with AD and mild cognitive impairment and can induce the activation of pro-inflammatory pathways leading to TNFα and IL1-β production." (PMID 28982375, 2017). "The cytokines IL-1β and TNF-α are widely described neuroinflammatory mediators associated with cognitive impairment." (PMID 28724382, 2017). "Pro-inflammatory cytokines, particularly IL-1β, TNF-α and IL-6, are associated with cognitive impairment." (PMID 29238302, 2017). "Studies indicate that high levels of the proinflammatory cytokines interleukin 1-β (IL1-β) and tumor necrosis factor-α (TNF-α) are associated with postoperative cognitive impairments." (PMID 28832497, 2017). "Overexpression of IL-1β in 3xTg AD mice exacerbated tau hyperphosphorylation within one month, while blocking IL-1β signaling via IL-1 receptor antagonist (IL-1ra) or anti-IL-1β antibody reversed the cognitive impairment with a diminished tau pathology." (PMID 27054030, 2016). "The restorative effects of pioglitazone and IL-1 RA demonstrated herein implicate a deleterious role of IL-1β in experience-dependent spine structural plasticity preceding cognitive impairment in AD." (PMID 26724934, 2016). "We therefore split the AD group into MMSE-tertiles and identified that with increasing cognitive impairment IL-1β levels are significantly increased compared with age-matched controls." (PMID 27671345, 2016). "So reduction of elevated TNF-α and IL-1β can restore neuronal function and reverse cognitive deficits post TBI." (PMID 26818584, 2016). "Increased IL-1β in hippocampus also mediates cognitive impairment following injection of lipopolysaccharide to mimic systemic infection or isoflurane exposure to mimic anesthetic-related cognitive dysfunction in aging." (PMID 26511444, 2015). "Treatment of anti-inflammation drug and blocking the signals of TNF-α and IL-1β all effectively decreased the cognitive impairment induced by surgery." (PMID 25198176, 2014). "Lidocaine, a local anesthetic with anti-inflammatory property, inhibited isoflurane-induced IL-1β increase and cognitive impairment." (PMID 23915963, 2013). "We showed here that isoflurane increased IL-1β and that lidocaine attenuated this increase and the isoflurane-induced cognitive impairment in the 18-month old rats." (PMID 23251531, 2012). "Our current study showed that lidocaine attenuated isoflurane-induced cognitive impairment and increase of hippocampal IL-1β and activated caspase 3 levels." (PMID 23251531, 2012). "Consistent with our findings, a recent study shows that cognitive impairment after an open tibial fracture fixation under general anesthesia in young adult mice is mediated by IL-1β." (PMID 23251531, 2012). "Thus, inflammatory cytokines IL-6, IL-1β, IL-13, and TNFα are elevated at this longer phase and are related to cognitive deficits and/or post-acute sequelae." (PMID 41516418, 2026). "Additionally, vitamin D supplementation ameliorated cognitive impairment and altered neurodegenerative (Aβ1-40, Aβ1-42, p-Tau, and Neprilysin) and inflammatory markers (IL-6, IL-1β, TNF-α, and NF-κβ) in the scopolamine-induced rat model." (PMID 41473190, 2025). "Furthermore, IL-1β overexpression can lead to neurodegeneration and cognitive impairment, while blocking IL-1β signaling attenuates tau pathology and rescues memory deficits in animal models." (PMID 41353558, 2025). "Moreover, subjects with cognitive impairment exhibited higher cytokine levels (both IL-1β and TNF-α) compared with subjects with normal cognition." (PMID 41149360, 2025). "The decline in cognitive function associated with inflammation may be reversible through IL‐1R depletion, suggesting that the IL‐1β signaling pathway is involved in cognitive impairments." (PMID 39996443, 2025).
Cognitive impairment (continued). "These associations are in agreement with previous reports showing that hypovitaminosis D predisposes individuals to different forms of cognitive impairment and the development of overt and covert HE, in line with the negative impact of IL-1β on brain function." (PMID 39861356, 2025). "Alisol A was shown to lead to neurovascular protection in cerebral ischemic mice through the activation of the AKT/GSK3β signaling pathway; the compound attenuated the neurological deficits and cognitive deficits and inhibited IL-6 and IL-1β expression, in addition to promoting neuronal survival." (PMID 40070574, 2025). "TNF-α and IL-1β are potent proinflammatory cytokines that induce neuronal death and cause sensory and cognitive deficits by mediating peripheral synaptic instability, whereas the inhibition of TNF-α and IL-1β has been associated with the alleviation of cognitive dysfunction." (PMID 39630234, 2025). "In addition, L. gasseri NK109 showed a protective effect that alleviated neuroinflammation and cognitive impairment by decreasing the expression of IL-1β and increasing the expression of the anti-inflammatory cytokine IL-10." (PMID 40002326, 2025). "The cognitive deficit could also be aggravated by high brain exposure to pro-inflammatory cytokines, including IL-1β, IL-6, and TNF-α." (PMID 39777720, 2025). "Our findings revealed that OI treatment significantly alleviated anesthesia/surgery-induced cognitive impairment, concomitant with reduced levels of the neuroinflammatory cytokines IL-1β and IL-6, as well as suppressed activation of microglia and astrocytes in the hippocampus." (PMID 38649932, 2024). "Reduced cognitive deficits in AD model mice; improved brain dendritic integrity and synaptic protein expression levels; inhibited microglia activation and reduced pro-inflammatory cytokines (IL-1β); reduced β-amyloid (Aβ) plaques in the hippocampus." (PMID 39149548, 2024). "Also, TNF and IL-1β are incriminated to disrupt the BBB, while IL-1β is linked to the degeneration of dopaminergic neurons and cognitive impairments, highlighting the role of inflammation in neurodegenerative processes." (PMID 39772122, 2024). "Surgical trauma can induce a sterile inflammatory response in the peripheral immune system, leading to the massive release of inflammatory mediators into the blood, subsequently inducing central nervous system overexpression of IL-1β, triggering cognitive impairment." (PMID 38649932, 2024). "Inhibiting IL-1β signaling can be improve cognitive impairment in certain disorders." (PMID 38665289, 2024). "The NLRP3 inflammasome complex is considered a possible therapeutic target for preventing various cognitive impairments due to its response to microbial infections and environmental stimuli, and it can activate caspase-1 and promote the maturation of IL-1β and IL-18." (PMID 39203778, 2024). "P. gingivalis periodontal infection may cause cognitive impairment or neuroinflammation via the release of the pro-inflammatory cytokines IL-6, TNF-α, and IL-1β." (PMID 38764065, 2024). "Second, it is possible that IL-1β signaling in a subpopulation of neurons (e.g., dentate gyrus) may be critical for post-injury cognitive deficits." (PMID 38435077, 2024). "Moreover, IL-1β has been concluded to be the final effector, contributing to inflammation-related cognitive dysfunction, while cognitive impairment is considered along with schizophrenia in its early stages." (PMID 37946206, 2023). "Together, these data indicate that IL-1β may be more closely linked to anxiety-like mood and sleep disorders, while TNF-α may be linked to depressive mood and cognitive abnormalities, which aligns with our findings." (PMID 37692303, 2023). "Consequently, aged rats but not young rats had significant increases in levels of ROS, expression of inflammatory cytokines TNF-α and IL-1β, activation of NF-κB and microglia in the hippocampus, and cognitive impairment following surgery." (PMID 36819786, 2023).
Cognitive impairment (continued). "It is generally acknowledged that neuroinflammation plays an important role in the pathogenesis of Alzheimer’s disease and there are more inflammatory markers (TNFα, IL-1β, IL-6, IL-10) in patients with AD and mild cognitive impairment (MCI) than in healthy controls." (PMID 37081917, 2023). "Our analysis revealed that, in patients with cognitive impairment due to AD, (i) sPECAM-1, sP-, sE-Selectins, and IL6 were associated with amyloid and tau pathology; (ii) sP-Selectin, sNCAM, and the decrease of IL10 with neurodegeneration; and (iii) LPS and IL1β with cognitive impairment." (PMID 37254223, 2023). "Accordingly, SARS-CoV-2, but not H1N1 influenza virus, increases levels of brain IL-1β and induces persistent IL-1R1-mediated loss of hippocampal neurogenesis, which promotes post-acute cognitive deficits." (PMID 37790551, 2023). "Here we proposed important ideas of IL‐1β, TNF‐α, and IL‐4; as the underlying CRCI pathway for coping with persistent psychological distress, as well as the potential evidence of psychological intervention to relieve cognitive impairment." (PMID 36965094, 2023). "Antibiotics or probiotic treatments, as well as IL-1β blocking could serve as promising therapeutic strategies for treating cancer-related cognitive impairment." (PMID 37400621, 2023). "In addition, IL-1β on D1 and IL-17 at baseline, D1, D3, and D7 correlated with elevated cognitive-impairment rate (all P<0.05)." (PMID 37878890, 2023). "Both in vivo and in vitro experiments showed that isoflurane could activate the NLRP3/caspase‐1 pathway and upregulate the secretion of IL‐18 and IL‐1β, and accelerate cognitive impairment." (PMID 38680509, 2023). "Similar to previous research results, our results show that Hsp22 overexpression pretreatment can inhibit the expression of NLRP3, Caspase-1, IL-1β and proinflammatory cytokines in hippocampal neurons, improve cognitive impairment in mice, and improve learning and memory capabilities." (PMID 36934348, 2023). "Moreover, earlier research has linked microglial activation, IL-1β elevation, and BDNF reduction to anesthesia- and surgery-induced hippocampus cognitive impairment." (PMID 36943623, 2023). "Moreover, microglial activation and production of proinflammatory cytokines and neurotoxic mediators, including interleukin-1 beta (IL-1β), tumor necrosis factor-alpha (TNF-ɑ), nitric oxide (NO), and ROS, can result in neuronal loss and cognitive deficits." (PMID 37081849, 2023). "However, in brain tissue from mdx mice, heightened levels of pro-inflammatory interleukin (IL)-1β and tumor necrosis factor (TNF)-α associated with several neurological diseases have been found and several cognitive deficits have also been observed." (PMID 37108685, 2023). "It was reported that the administration of MCC950 could inhibit the level of NLRP3, ASC, and IL-1β in hippocampus and ameliorate cognitive impairment in db/db mice." (PMID 35955939, 2022). "It has been shown that IL-1β and IL-6 play roles in regulating cognitive function; blocking IL-1β in AD mouse models protects against cognitive deficits, and the upregulation of IL-6 contributes to cognitive deficits in humans." (PMID 34958017, 2022). "Fisetin‐blocked NLRP3 inflammasome activation via promoting mitophagy in CMECs may suppress the secretion of IL‐1β into CNS, reduce neuroinflammation, and contribute to the amelioration of cognitive impairment." (PMID 34837343, 2022). "Overall, the IL-1β model failed to reproduce the main lesions of the AD pathology despite the confirmation of the association between chronic neuroinflammation and cognitive deficits." (PMID 35163653, 2022). "Therefore, this evidence from our current study and other suggests that elevated systemic IL-1β infiltrates the brain and causes aberrant astrocytic GABA production, leading to cognitive impairment in RA." (PMID 35982301, 2022).
Cognitive impairment (continued). "Collectively, fisetin‐blocked NLRP3 inflammasome activation via promoting mitophagy in CMECs may suppress the secretion of IL‐1β into CNS, reduce neuroinflammation, and contribute to the amelioration of cognitive impairment." (PMID 34837343, 2022). "After long-term isoflurane anesthesia, the GJs formed by Cx43 in the mouse hippocampus and primary mouse astrocytes were significantly reduced, GJs function was impaired, hemichannel activity was enhanced, the levels of IL-1β and IL-6 were increased, and mice showed significant cognitive impairment." (PMID 35255943, 2022). "The present study reveals that neonatal severe inflammation can induce long-lasting cognitive impairment in adolescent rats via upregulation of IL-1β/KCC2 signaling during neonatal development, accompanied by accelerating GABAergic shift from depolarizing to hyperpolarizing." (PMID 35883093, 2022). "Our previous studies indicated that peripheral burns and traumatic surgical wound could induce the dysfunction of BBB and thus cognitive impairment through IL-6 and IL-1β." (PMID 36353359, 2022). "Dexmedetomidine could reduce the incidence of cognitive impairment after intestinal I/R injury, which may be related to decreased levels of inflammatory cytokines IL-1β, IL-6, C-reactive protein, and TNF-α." (PMID 35945306, 2022). "In addition, high TNF-α (P<0.001, adjusted P <0.001), IL-1β (P=0.033, adjusted P=0.132), and IL-6 (P=0.012, adjusted P=0.048), but not IL-17 (P=0.554, P=1.000 after adjustment) were correlated with cognition impairment occurrence." (PMID 35239774, 2022). "Sustained elevation of IL-1β in the hippocampus may induce cognitive impairment by upregulation of KCC2 during early development." (PMID 35883093, 2022). "Notably, knockdown of the expression of IL-1β significantly alleviated the long-lasting cognitive impairment induced by neonatal inflammation, confirming the important role of sustained elevated levels of IL-1β in this disorder." (PMID 35883093, 2022). "Therefore, our findings indicate that the upregulation of KCC2 during development mediated the effects of elevated IL-1β levels on long-lasting cognitive impairment." (PMID 35883093, 2022). "A study of recurrent neonatal seizures (RNS) has shown an evident up-regulation in the expression of TNF-α and IL-1β as well as a remarkable increase of NF-κB activity in both the cortex and hippocampus of the RNS brain, which were associated with cognitive impairment." (PMID 35974336, 2022). "Diabetic rats administered TDF exhibited cognitive deficits; and increases in blood glucose, malondialdehyde, and interleukin-1 beta (IL-1β) levels, which correlate with decreases in glutathione level, and superoxide dismutase (SOD) and catalase (CAT) activities." (PMID 35122679, 2022). "Animal experiments also found that pain may aggravate cognitive impairment by changing the levels of inflammatory factors such as IL-6 and IL-1β in the plasma of rats." (PMID 33730999, 2021). "Recently, Guo and colleagues hypothesized that NLRP3 induction in visceral adipose tissue (VAT) could initiate central microglial activation and cognitive impairment by increasing IL-1β." (PMID 34070553, 2021). "HIV-1 Tat protein exerts proinflammatory effects on microglia, astrocytes and neurons that produce key pro-inflammatory cytokines, such as tumor necrosis factor-alpha (TNF-α) and interleukin-1 beta (IL-1β), which ultimately lead to neuron damage and cognitive deficits." (PMID 34358137, 2021). "Besides, HFD-induced obese mice exhibit increased IL1β secretion in the hippocampus, which leads to cognitive impairment." (PMID 34720877, 2021). "Similarly to IL-1β, also TNFα, at levels over the physiological range, leads to hippocampal LTP impairment associated with depressive-like behavior and cognitive deficits in animal models." (PMID 33732142, 2021).